SFRP4 (secreted frizzled related protein 4)
Diseases named in the same sentence as SFRP4 in open-access papers (continued):
Sharing a sentence is not in itself a finding about the gene and the disease.
melanoma (3 papers, 2010 to 2023). A malignant, usually aggressive tumor composed of atypical, neoplastic melanocytes. "Subsequently, we conducted a joint analysis of proteomic data and TCGA human melanoma RNA-seq data, and found that the mRNA and protein levels of 34 genes, including DSE, VEPH1, SFRP4, TTN, STSE, were consistently down-regulated in melanoma tissues." (PMID 37833287, 2023). "Similarly, SFRP4, a member of the secreted frizzled-related protein family and a negative regulator of the Wnt pathway that is frequently epigenetically silenced in various tumor types was observed to be gained and overexpressed in 4 of 72 of metastastic melanomas in this study." (PMID 20520718, 2010).
renal fibrosis (3 papers, 2015 to 2020). A final common manifestation of a wide variety of chronic kidney diseases characterized by glomerulosclerosis and tubulointerstitial fibrosis. "Corresponding with this, it was found that an increase in sFRP4 led to a decrease in β-catenin signalling and a decrease in the progression of renal fibrosis." (PMID 32365994, 2020). "Whilst further investigations found that these data correlate with a faster decline in renal function, other research has displayed that a decrease in sFRP4 relates to an increase in β-catenin signalling and an increase in the progression of renal fibrosis." (PMID 32365994, 2020). "On the other hand, Sfrp4 administration in rats reduces fibrosis after ischemic injury to the heart, and a therapeutical effect of recombinant Sfrp4 on renal fibrosis in mice has been described." (PMID 26635199, 2016). "Wnt signaling has been implicated in the pathogenesis of renal fibrosis based on the findings that expression of Wnt ligands is upregulated in fibrotic kidneys, and inhibition of Wnt signaling using DKK-1, sFRP4 or paricalcitol can reduce renal fibrosis in mice." (PMID 26092126, 2015).
serous ovarian cancer (3 papers, 2012 to 2021). "Whilst a clear cell and endometrioid ovarian cancer cell line (TOV21D, TOV 112D, respectively) expressed SFRP4 at similar levels to one of the tubal controls, the undifferentiated serous ovarian cancer cell line (SKOV3) displayed very low levels of SFRP4." (PMID 22363760, 2012). "Here we show that recombinant SFRP4 (rSFRP4) treatment of a serous ovarian cancer cell line results in inhibition of β-catenin dependent Wnt signalling as measured by TOP/FOP Wnt reporter assay and decreased transcription of Wnt target genes, Axin2, CyclinD1 and Myc." (PMID 23326605, 2013). "Our experiments contradict a previous small study where SFRP4 expression was measured by IHC in 153 serous ovarian cancers and no survival effect could be found." (PMID 22363760, 2012).
stomach cancer (3 papers, 2017 to 2025). "We further confirmed that the protein level of SFRP4 expression was significantly elevated in gastric tumor tissues compared with normal tissues." (PMID 40565036, 2025). "UALCAN analysis of TCGA data revealed that SFRP4 is significantly upregulated in primary gastric tumors versus normal gastric mucosa." (PMID 40565036, 2025). "Collectively, these data demonstrate that SFRP4 is overexpressed in gastric tumors, exhibits intratumoral heterogeneity, and serves as an adverse prognostic indicator across diverse patient cohorts." (PMID 40565036, 2025).
Arrhythmia (2 papers, 2020 to 2025). Any cardiac rhythm other than the normal sinus rhythm. "Multiple downstream genes regulated by TBX5, F2R, and SFRP4 were involved in ICM-related diseases such as HF and arrhythmia." (PMID 32423033, 2020). "Furthermore, downstream genes (MYH6, MYH7, TNNT2, NKX2-5, and CCND1) regulated by SFRP4 partake in ICM-related diseases like HF and arrhythmias." (PMID 40066352, 2025).
colorectal tumor (2 papers, 2024 to 2026). "Top genes included SFRP4 and ANGPTL1, which are both implicated in colorectal tumor aggressiveness." (PMID 41363728, 2026).
endometrial stromal sarcoma (2 papers, 2017 to 2021). "Compared to normal endometrium, the expression of SFRP4 was decreased in both low-grade endometrial stromal sarcoma and undifferentiated endometrial sarcoma, and it was regulated in an opposite manner to that of β-catenin." (PMID 34771683, 2021). "However, another member of the SFRP family, SFRP4, was found to be downregulated in a rare uterine tumor, the endometrial stromal sarcoma, as revealed by cDNA arrays." (PMID 34771683, 2021).
gastric adenocarcinoma (2 papers, 2022 to 2025). "Although SFRP4 ranked among the most differentially expressed genes in stomach adenocarcinoma (STAD) through whole-transcriptome profiling, its expression varied widely across individual tumor samples, suggesting context-dependent regulation." (PMID 40565036, 2025). "That assessment matched our findings that SFRP4 was overexpressed in STAD (stomach adenocarcinoma) tissues." (PMID 35847366, 2022). "To further explore whether there is an association between SFRP4 expression and the immune microenvironment, we analyzed the relationship between SFRP4 expression levels and immune components in gastric adenocarcinoma patients using the TISIDB database." (PMID 35847366, 2022).
interstitial lung disease (2 papers, 2021 to 2022). A diverse group of lung diseases that affect the lung parenchyma. "In particular, single cell RNAseq revealed increased SFRP4 in a distinct subgroup of fibroblasts isolated from SSc-interstitial lung disease (ILD) biosamples, which were hypothesised to be progenitors of myofibroblasts." (PMID 34945116, 2021). "In particular, single-cell RNAseq revealed increased SFRP4 in different subgroups of fibroblasts isolated from systemic sclerosis interstitial lung disease (ILD) biosamples, which were hypothesized to be progenitor cells of myofibroblasts." (PMID 36084952, 2022).
liver cancer (2 papers, 2014 to 2025). An epithelial or non-epithelial malignant neoplasm that arises from the liver. "In line with this, clinical studies have linked high SFRP4 expression to favorable outcomes in breast, ovarian, and liver cancers, yet in the stem-like subtype of GC, it portends markedly worse prognosis." (PMID 40565036, 2025).
lymph node metastases (2 papers, 2017 to 2021). "Similarly, western blotting revealed that, compared with patients with regional lymph node metastases (LN+), patients without regional lymph node metastases (LN-) had a high SFRP4 expression ratio of normal tissue to tumor tissue." (PMID 28977937, 2017).
metastatic disease (2 papers, 2010 to 2015). "When comparing methylation rates in localized tumors versus metastatic disease, the methylation of RUNX3 (p = 0.013), SCGB3A1-2 (p = 0.008), SFRP4-2 (p = 0.022), and DLC1 (p = 0.016) was significantly associated with the presence of metastatic disease." (PMID 20849603, 2010). "Methylation of RUNX3, SCGB3A1, SFRP4, and DLC1 was significantly associated with the extent of the disease when comparing localized versus metastatic tumors." (PMID 20849603, 2010).
oral submucous fibrosis (2 papers, 2022 to 2025). "Another microRNA involved in EMT regulation is miR-203, a significantly upregulated microRNA in oral submucous fibrosis compared to normal oral mucosa, which can become a decisive factor for malignant transformation of oral submucous fibrosis by targeting SFRP4 and TM4SF1." (PMID 41303164, 2025).
osteopetrosis (2 papers, 2020 to 2024). Osteopetrosis, also known as marble bone disease, is a descriptive term that refers to a group of rare, heritable disorders of the skeleton characterized by increased bone density on radiographs. "Among the screened genes, we noticed Sfrp4, the human pathogenic gene for osteopetrosis, was downregulated in OsxCre;R26dn/dn osteoblasts." (PMID 39419968, 2024).
ovarian tumours (2 papers, 2012 to 2017). "In summary, sFRP4 chemo-sensitizes CSCs derived from breast, prostate, and ovary tumor cell lines by reducing their pro-oncogenic profile, stemness capacity, cell survival protein and oncogene expression, making them more responsive to chemotherapeutic drugs." (PMID 28536422, 2017). "Our data are the first to demonstrate that sFRP4 not only plays a key role in the chemo-response of ovarian tumours but can enable these cells to respond better to Cisplatin treatment when up-regulated in chemoresistant cells." (PMID 23039795, 2012). "The differential expression of sFRP4 seen in the chemosensitive and chemoresistant cell lines indicated that sFRP4 could serve as a prognostic marker for ovarian tumours." (PMID 23039795, 2012). "We further examined sFRP4 expression in human ovarian tumours to assess if its expression could be correlated with clinico-pathological features consistent with a proposed role for loss being a contributor to chemoresistance." (PMID 23039795, 2012).
pancreatic ductal adenocarcinoma (2 papers, 2021 to 2025). An infiltrating adenocarcinoma that arises from the epithelial cells of the pancreas. "Previous studies have shown that SFRP4 is associated with regulatory T cell (Treg) infiltration in pancreatic ductal adenocarcinoma." (PMID 39729237, 2025). "Previous studies showed that SFRP4 correlates with Treg cell infiltration in pancreatic ductal adenocarcinoma." (PMID 34205081, 2021).
pituitary adenoma (2 papers, 2015 to 2024). "A review of 13 whole genome approaches in pituitary tumors with the goal of identifying Wnt family inhibitors showed that expression of WF1, SFRP2, FRZB, SFRP4, DKK2, and SOSTDC1 genes is decreased in pituitary adenomas compared to normal pituitary tissue, while that of SFRP1 and SFRP4 is increased." (PMID 25834571, 2015).
pituitary tumor (2 papers, 2015 to 2023). A benign or malignant neoplasm affecting the pituitary gland. "For example, expression of the Wnt decoy receptors sFRP2, sFRP4, and Wif1 are downregulated in pituitary tumors by epigenetic mechanisms." (PMID 36965619, 2023).
prediabetes (2 papers, 2024 to 2025). "miR-34a showed consistent elevation across obese prediabetes cohorts, targeting TNFα, procalcitonin, and Wnt signaling modulators such as SFRP4." (PMID 41400625, 2025). "The present study demonstrated that patients with prediabetes and T2D have increased levels of SFRP4 protein in their plasma." (PMID 38834984, 2024). "In turn, prediabetes subjects had higher SFRP4 concentrations than control subjects (P < 0.05)." (PMID 38834984, 2024). "Interestingly, the concentration of SFRP4 was correlated with high levels of proinflammatory molecules in the prediabetes and T2D groups." (PMID 38834984, 2024). "Prediabetes and T2D patients had significantly higher SFRP4 levels than controls (P < 0.05)." (PMID 38834984, 2024). "The T2D group had the highest levels of SFRP4 compared with the prediabetes and control groups." (PMID 38834984, 2024). "Hence, in a cohort study, we would be able to follow up the patients with prediabetes and observe the incidence of T2D to correlate the incidence with SFRP4 concentrations, and therefore evaluate SFRP4 as a prognostic factor for T2D." (PMID 38834984, 2024). "We aimed to evaluate the role of SFRP4 in prediabetes and T2D in a Mexican population." (PMID 38834984, 2024).
scleroderma (2 papers, 2021 to 2022). Scleroderma is a rare autoimmune connective tissue disorder characterized by abnormal hardening of the skin and, sometimes, other organs. "Secreted Frizzled Receptor Protein 4 (SFRP4) has been shown to be increased in Scleroderma (SSc)." (PMID 34945116, 2021).
Stroke (2 papers, 2014 to 2017). Sudden impairment of blood flow to a part of the brain due to occlusion or rupture of an artery to the brain. "The association of higher SFRP4 concentrations with stroke/TIA seems to be a hit by chance since significance was rapidly lost upon multivariable adjustment." (PMID 25408147, 2014).
systemic sclerosis (2 papers, 2016 to 2022). A chronic disorder, possibly autoimmune, marked by excessive production of collagen which results in hardening and thickening of body tissues. "In humans with systemic sclerosis, an upregulation of SFRP4 on mRNA and protein level was found in fibrotic skin." (PMID 26635199, 2016).
ulcerative colitis (2 papers, 2025). An inflammatory bowel disease involving the mucosal surface of the large intestine and rectum. "In this study, the methylation and expression status of SFRP2, SFRP4, SFRP5, APC1, and APC2 genes were evaluated for the first time in ulcerative colitis patients in the Turkish population." (PMID 40521787, 2025). "In ulcerative colitis, inflammation is thought to be associated with both increased APC2 methylation and decreased expression findings due to decreased SFRP4 methylation in non-inflamed areas." (PMID 40521787, 2025).
age (1 paper, 2023). A temporal measurement of the time period elapsed since an identifiable point in the life cycle of an organism. "Secreted Frizzled-Related Protein 4 (sFRP4) is an extracellular Wnt antagonist, and sFRP4 gene interference can activate the Wnt/β-catenin signalling pathway and relieve age-related bone loss." (PMID 37891477, 2023).
allergic asthma (1 paper, 2020). A asthma with a basis in a pathological type I hypersensitivity reaction. "Furthermore, in an asthma mouse model, it has been demonstrated that miR-943-3p can negatively regulate the expression of SFRP4, causing accelerated progression of airway remodeling in allergic asthma." (PMID 32956382, 2020).
aortic atherosclerosis (1 paper, 2023). A atherosclerosis that involves the aorta. "The findings of this study demonstrate that overexpression of SFRP4 significantly inhibits aortic atherosclerosis through multiple signaling pathways except for inflammation and oxidative." (PMID 37143778, 2023). "After 12 weeks, lipid profiles, aortic atherosclerosis, and RNA sequence analysis of differential gene expression were evaluated in the aorta of the Ad-SFRP4 injected mice and their control counterparts (Ad-GFP injected)." (PMID 37143778, 2023).
astrocytomas (1 paper, 2024). "The increase in astrocytoma grade resulted in SFRP4 protein decrease (p = 0.008), indicating the loss of its antagonistic role in Wnt signaling." (PMID 38993819, 2024). "Our study demonstrated that the protein levels of this Wnt antagonist were generally low with only 6% of our total astrocytoma sample showing strong expression of SFRP4 protein." (PMID 38993819, 2024). "Pearson’s χ2 - test showed statistically significant differences in methylation status of the SFRP4 gene between astrocytoma malignancy grades (p < 0.001)." (PMID 38993819, 2024). "The increase in astrocytoma grade leads to a decrease in SFRP4 protein expression suggesting that SFRP4 acts as a tumor suppressor and inhibits the activity of the Wnt signaling." (PMID 38993819, 2024). "Weak expression of the SFRP4 protein was observed in 28.5% of astrocytoma samples with methylated promoters and 78% of unmethylated samples." (PMID 38993819, 2024). "Analysis of 49 astrocytoma samples showed that 16.3% (8/49) of cases had a methylated SFRP4 promoter while 83.7% (41/49) had an unmethylated one." (PMID 38993819, 2024). "Additional research is indicated to determine the mechanism, genetic or epigenetic, that is behind SFRP4 lowered expression in higher astrocytoma grades." (PMID 38993819, 2024). "Promoter methylation status, expression levels and localizations of Secreted Frizzled Related Protein 4 (SFRP4) protein in astrocytoma samples and patients’ survival." (PMID 38993819, 2024). "We can speculate that methylation of SFRP4 confined only to grade 2 astrocytomas may act as “driver methylation” that initially inactivates relevant suppressor gene." (PMID 38993819, 2024). "SFRP4 is an interesting molecular factor in the occurrence and development of astrocytomas." (PMID 38993819, 2024). "Promoter methylation of the SFRP4 gene in astrocytoma samples was examined by the MS-PCR." (PMID 38993819, 2024). "Our analysis of methylation status of SFRP4 gene across astrocytoma grades showed that the majority of samples (83.7%) did not have methylated promoter." (PMID 38993819, 2024). "Results of the MS-PCR reaction showed the presence of SFRP4 promoter methylation in the majority of diffuse astrocytoma samples and the absence of methylation in higher astrocytoma grades." (PMID 38993819, 2024). "SFRP4 expression in a total of 50 astrocytomas of different grades showed low or lack of expression in 72% (36/50), moderate in 22% (11/50) and strong in 6% (3/50) of cases." (PMID 38993819, 2024).
benign prostatic hyperplasia (1 paper, 2024). A non-cancerous nodular enlargement of the prostate gland. "To explore the cellular origin of SFRP4, we analyzed the publicly available single-cell transcriptomics dataset from the Strand lab29,30, generated from prostates of healthy organ donors and patients treated for benign prostatic hyperplasia." (PMID 39511287, 2024).
blood disease (1 paper, 2021). A disease that occurs in the blood. "The top candidates include TNFAIP3, which has been reported before, but also include other, novel regions, containing genes involved in blood diseases (CYCS), neurological diseases (PRKCH, KCNH5, LRNN1), metabolism (SFRP4, SUMF1), and skin development (ASCL4, RAB27A)." (PMID 34032215, 2021).
breast tumour (1 paper, 2022). "Mass spectrometric data from 125 breast tumour samples showed CTHRC1, POSTN and MMP13 to all be significantly higher in breast tumour tissue relative to normal while SFRP4 and FNDC1 levels were unaffected." (PMID 36190948, 2022).
chronic gastritis (1 paper, 2021). Inflammation of the stomach that is chronic in nature. "Compared to normal gastric mucosa (n = 7) the premalignant conditions chronic gastritis (n = 22, p = 0.0077) and intestinal metaplasia (n = 21, p = 0.0031) both demonstrated elevated SFRP4 expression." (PMID 33277667, 2021).
chronic heart failure (1 paper, 2024).
chronic myeloid leukemia (1 paper, 2025). "Similarly, the Wnt signaling pathway inhibitor sFRP4 showed an increase in 5hmC and was reported to be promoter-methylated in chronic myeloid leukemia." (PMID 41516186, 2025).
colorectal adenoma (1 paper, 2024). An adenoma that arises from the colon or rectum. "SFRP4 was downregulated or silenced in 9.1% of colorectal adenomas relative to the normal mucosa." (PMID 38993819, 2024).
craniosynostosis (1 paper, 2011). Craniosynostosis is defined as the premature fusion of one or more cranial sutures leading to secondary distortion of skull shape resulting in skull deformities with a variable presentation. "SFRP4 has been shown to antagonize Wnt activation supporting previous reports that Wnt signaling plays a role in the pathogenesis of craniosynostosis." (PMID 22028906, 2011). "After controlling for variables contributing to potential bias, FGF7, SFRP4, and VCAM1 emerged as genes associated with single-suture craniosynostosis due to their significantly large changes in gene expression compared to the control population." (PMID 22028906, 2011). "The results from this study not only identified FGF7, SFRP4, and VCAM1 as novel genetic candidates for the cause of single-suture craniosynostosis like, but also confirmed the involvement of ECM-mediated focal adhesion and Ffg/Wnt/Igf signaling pathways that may contribute its pathogenesis." (PMID 22028906, 2011).
cyst (1 paper, 2023). A sac-like closed membranous structure that may be empty or contain fluid or amorphous material. "Secreted frizzled-related protein 4 (sFRP4), an antagonist of the Wnt signaling pathway, is highly expressed in kidneys, blood, cyst fluid and urine of ADPKD patients." (PMID 38027263, 2023).